CRP (C-reactive protein)
Diseases named in the same sentence as CRP in open-access papers (continued):
Sharing a sentence is not in itself a finding about the gene and the disease.
COVID-19 (continued). "With a sensitivity of 92% and a specificity of 65–67%, IL-6 ≥ 52.8 pg/ml, PCT ≥ 0.11 ng/ml, and CRP ≥ 71.1 mg/L were predictive of a severe course of COVID-19." (PMID 37937220, 2023). "The results also showed that the majority of COVID-19 pregnant women had elevated CRP levels, namely 14 people (12.5%), and non-COVID-19 pregnant women had normal CRP levels, namely 98 people (87.5%)." (PMID 37822551, 2023). "This study highlights the significant impact of COVID-19 on the liver and how high levels of CRP can increase the chances of acute liver injuries." (PMID 37363445, 2023). "This test highlighted significant differences between the three groups of COVID-19 severity in IL-6 concentrations, CRP, % neutrophils, lymphocyte count, % lymphocytes, eosinophil count, % eosinophils, NLR, PLR, and urea." (PMID 36838284, 2023). "Studies have reported significant laboratory abnormalities such as lymphopenia, neutrophilia, hypoalbuminemia, and elevated CRP, procalcitonin and D-dimer levels were seen in patients infected with severe COVID-19,5-8 which is consistent with our findings." (PMID 36950410, 2023). "The present study illustrated significant increases in median CRP levels in patients with bacterial pneumonia compared to patients with COVID-19 and the control group." (PMID 38585537, 2023). "Atorvastatin significantly reduces supplemental oxygen need, hospitalization duration, and serum hs-CRP level in mild to moderate hospitalized COVID-19 patients." (PMID 37920591, 2023). "NLR and CRP levels increased more in the severe COVID-19 group compared with the mild/moderate group." (PMID 36838284, 2023). "To investigate these interactions, we performed a retrospective analysis evaluating the relationship between the CRP level and illness severity in adults who were admitted to a large New Jersey (USA) tertiary care hospital during the first COVID-19 wave." (PMID 38003780, 2023). "COVID-19 patients had highermean blood glucose, C-reactive protein, and lactic dehydrogenase levels thannon-COVID-19 patients." (PMID 38265317, 2023). "In the current study, we noticed significant alterations of systemic inflammatory markers such as ESR, CRP, and ferritin being highest during COVID-19 with partial improvement after recovery." (PMID 37312131, 2023). "Previously, it was noted that the probability of developing a severe course of disease increases by 5% for each unit of increase in the level of CRP in patients with COVID-19." (PMID 36975366, 2023). "The results of abnormal laboratory findings reported in the articles indicate elevated CRP and D-dimer levels, lymphopenia, leukopenia, and acute kidney injury among NH residents confirmed to have COVID-19." (PMID 36803435, 2023). "The chemokine MCP-1 levels were increased in post-COVID-19 female patients and maintained a positive correlation with the CRP levels in the post-COVID-19 patients." (PMID 37896963, 2023). "CRP is a well-known acute phase reactant that can be easily measured, and its levels have been correlated with disease severity in COVID-19." (PMID 37900075, 2023). "In other words, individuals with high fibrinogen relative to CRP on admission tend to have signs of objective and subjective cognitive deficits at 6 and 12 months after COVID-19." (PMID 37653345, 2023). "The levels of both IL-6 and CRP rise substantially during the fulminant course of COVID-19, with sharply rising CRP levels often preceding the patient’s respiratory collapse." (PMID 37626775, 2023). "In conclusion, NLR and CRP, which are cheap and widely available tools, show different time courses during hospitalization in COVID-19 patients, with a characteristic pattern depending on outcome." (PMID 37373750, 2023). "Serum level of CRP was significantly elevated in both bacterial pneumonia and COVID-19 but significantly higher among patients with bacterial pneumonia." (PMID 38585537, 2023).
COVID-19 (continued). "In this study, the median CRP mg/dl of patients with COVID-19 was significantly increased compared to the healthy control, with a greater increase among patients with moderate clinical manifestations than those with mild disease." (PMID 38585537, 2023). "During acute COVID-19, CRP (16.37 vs 3.5 mg/dL, P = .018) and IL-6 concentrations (130.8 vs 41.6 ng/L, P = .009) were significantly higher and Trp levels (42.2 vs 51.8 μmol/L, P = .046) lower in patients with sleeping difficulties." (PMID 37038445, 2023). "It was observed that an increase in lymphocytes (CD4 and transiently CD45RARO) resulted in lower CRP levels, perhaps leading to COVID-19 recovery and immune response homeostasis." (PMID 36986336, 2023). "Compared to healthy controls, the median CRP of patients with COVID-19 was considerably higher (P<0.000)." (PMID 38585537, 2023). "Patients with COVID-19 experience large increases in inflammatory cytokines and C-reactive protein (CRP)." (PMID 37187644, 2023). "Further large-scale studies are needed to confirm the study findings on the relationship between CRP and COVID-19-related prothrombotic state." (PMID 36619223, 2023). "The study found that autoantigens like NXPH-1, PCSK-1, SLC2A10, and DCD correlated with markers of COVID-19 severity like D-dimers, ferritin, C-reactive protein, and lactate which can increase in severe COVID-19." (PMID 36937488, 2023). "The clusters significantly differed in natural COVID-19 parameters, such as CRP, chest X-ray findings and MEWS score, suggesting that the clusters are different in terms of the state of the disease." (PMID 37258639, 2023). "All of the COVID-19 patients had elevated CRP levels: 75.7 mg/L (SD = 73.7) in the CKD group and 53.9 mg/L (SD = 59.5) in the non-CKD group." (PMID 36983566, 2023). "LDH levels in patients with COVID-19 correlated significantly with CRP (ρ = 0.31, p = 0.024), albumin (ρ = -0.40, p = 0.002), CKMB_M (ρ = 0.31, p = 0.028), and myoglobin (ρ = 0.29, p = 0.036)." (PMID 37965268, 2023). "Because it responds so quickly to the inflammatory process and COVID-19 patients have dramatically higher levels, the acute-phase reactant CRP is crucial for these individuals." (PMID 37363608, 2023). "It has been reported that the levels of D-dimer and C-reactive protein (CRP) are notably increased in individuals suffering from COVID-19." (PMID 36999046, 2023). "To better picture the general landscape of CRP and of the other 12 biomarkers serum levels in moderate and severe COVID-19 patients, we further investigated the correlation coefficients between any combination of bio-signatures." (PMID 37388734, 2023). "The result of our study thus confirms the importance of CRP as a marker of disease severity and adds to the body of evidence that CRP is also an independent clinical factor and a potential predictor of poor outcomes of COVID-19 in the elderly population." (PMID 36814202, 2023). "Using creatinine, albumin, CRP, white blood cell count and clinical characteristics five phenotypes of hospitalized COVID-19 patients were identified." (PMID 37507773, 2023). "Critically ill APLA-positive COVID-19 patients had higher median concentrations of CRP and D-dimer and were more likely to have a critical clinical course and fatal outcome." (PMID 37626797, 2023). "Patients with critical and severe COVID-19 had significantly higher serum concentrations of CRP and IL-6, glucose, urea, AST, LDH and CK at the time of admission." (PMID 37893159, 2023). "Other clinical studies reported positive correlation between elevated plasma CRP levels and myocardial infarct size, reduced lung function in chronic obstructive pulmonary disease or the severity of COVID-19-evoked respiratory distress." (PMID 37564640, 2023). "It has been reported that 20 out of 32 studies showed that the risk of poor outcomes was approximately four times higher in COVID-19 patients with high CRP." (PMID 36919085, 2023).
COVID-19 (continued). "of 140 COVID-19 patients reports a 67.9% and 65% rise in IL-6 and CRP protein levels in serum, which corresponding to the severity of the disease." (PMID 37649125, 2023). "The results of our study confirm that D-dimer, fibrinogen, and CRP are biomarkers of inflammation and hypercoagulation that serve as predictors of immunothrombosis affecting the severity of COVID-19." (PMID 37390087, 2023). "Based on the data of the present study, although CRP reached the normal value on day 28 in patients with COVID-19, the levels of several subpopulation of T cells remained elevated." (PMID 37034572, 2023). "Another study found EOS# to be a significant element in the triage of COVID-19-positive patients, together with CRP." (PMID 37570378, 2023). "Pregnant women in Group II, who had a severe course of COVID-19, showed significantly higher levels of CRP and procalcitonin compared to pregnant women in Group I, who had a mild course of the disease." (PMID 37520486, 2023). "The multivariate statistical analysis reported that Leukocytes, Platelets count, NLR, D-dimer, and CRP predicted mortality of COVID-19 patients, and CRP was the best predictor for mortality." (PMID 37484181, 2023). "According to the f test of the One-Way ANOVA, there were significant differences between the three severity groups of COVID-19 in IL-6, CRP, % neutrophils, lymphocyte count, % lymphocytes, eosinophil count, % eosinophils, NLR, PLR, and urea." (PMID 36838284, 2023). "A meta-analysis study showed marked elevations in inflammatory markers such as ESR, CRP, serum ferritin, and IL-2, -6, and -10 in patients with severe COVID-19, which were also noted in this study." (PMID 37398817, 2023). "It was shown in many studies that the CRP value increased in COVID-19 patients; in critical form patients, it reached values 5 to 10 times higher than those in non-severe patients." (PMID 37239895, 2023). "According to the evidence, COVID-19 induces a substantial increase in CRP levels due to the resulting inflammatory response." (PMID 37363445, 2023). "Areas under the curve (AUC) have been reported for the predicting mortality of COVID-19, which is equal to 0.899, 0.956, 0.797, 0.879, and 0.989, for Ct value, D-dimer, CRP, SpO2, and their combinations, respectively." (PMID 36999046, 2023). "DPP3 showed a significant and positive correlation with IL-6 (ρ = 0.50, p < 0.001), CRP (ρ = 0.46, p < 0.001), and leucocytes (ρ = 0.20, p < 0.05) in COVID-19 patients." (PMID 37733154, 2023). "We propose a predictive model based on CART analysis for pneumonia in patients with COVID-19, consisting of four predictors: CRP level, age, LDH level, and Hb level." (PMID 37720137, 2023). "The efficacy of mebendazole in COVID-19 patients was evaluated using PCR cycle threshold (CT) elevation, CRP levels, and differential changes in WBC on day 3 between the drug group and the placebo group." (PMID 37375747, 2023). "CRP Patterns B and C were significantly more present in COVID-19 patients with ICU-acquired infection." (PMID 37834754, 2023). "A previous investigation found that 9.5% to 16.0% of individuals who recovered from COVID-19 still had high CRP levels (≥ 5 mg/L) in the second month after hospital discharge." (PMID 37653091, 2023). "In patients with severe COVID-19, the CRP values were significantly higher compared to patients with a mild form of the disease." (PMID 36975366, 2023). "Other studies have shown that the administration of infliximab (anti-TNF-α antibody) reduced IL-6 and CRP levels in COVID-19 cases." (PMID 37854602, 2023). "Teicoplanin and alpha 1-antitrypsin are poorly studied drugs in the context of COVID-19, but they have shown positive results in severe COVID-19, as they have been reported to decrease the mortality rate and CRP concentration." (PMID 37109231, 2023). "Lactate dehydrogenase (LDH), D-dimer, ferritin, and C-reactive protein (CRP) biomarkers often increase in serious COVID-19 cases and poor prognosis." (PMID 37754237, 2023).
COVID-19 (continued). "Previous COVID-19 studies have suggested that the blood plasma laboratory values of PCT as well as others such as CRP, D-dimer, etc., are often elevated in patients with COVID-19 who required ICU admission, mechanical ventilation (MV), or those who died." (PMID 37068086, 2023). "In patients with COVID-19, it has been repeatedly documented and clinically seen that this monoclonal antibody quickly reduces fever and blood CRP levels." (PMID 36833140, 2023). "Some patients with COVID-19 have had elevated white blood cell counts and C-reactive protein levels." (PMID 37646728, 2023). "In this study, it was found that the increase of CRP, LDH levels and the drop of albumin level in the blood are laboratory parameters that were associated with increased COVID-19 severity." (PMID 37376524, 2023). "Another study of 198 COVID-19 patients found that the BAR was a better predictor of disease severity than NLR or CRP levels." (PMID 38074058, 2023). "For instance, the RECOVERY trial found that tocilizumab improved the clinical outcomes of COVID-19 patients with hypoxia (oxygen saturation < 92%) and CRP levels ≥ 7.5 mg/dL." (PMID 37081872, 2023). "In a review article, most of the reviewed studies reported increased CRP levels in severe forms of COVID-19." (PMID 37568161, 2023). "In patients with severe COVID-19, there is a remarkable increase in serum CRP, indicating an enhanced systemic inflammatory response." (PMID 36832234, 2023). "Identifying a CRP cut-off value of >29.8 mg/L in our study has practical implications for the daily management of COVID-19 patients." (PMID 37900075, 2023). "Many authors believe that bacterial infections that occur in patients with severe COVID-19 symptoms are directly related to high CRP and PTC levels." (PMID 36900724, 2023). "In our previous study we found that both NLR and CRP are reliable prognostic predictors in COVID-19 patients." (PMID 37373750, 2023). "In the case of patients diagnosed with moderate and severe forms of COVID-19, the variation in biological tests has shown high concentrations for serum glucose, lactate dehydrogenase and C-reactive protein." (PMID 38248722, 2023). "Patients from the severe group were clearly older than the other groups and exhibited higher CRP levels and higher viral loads than that of the symptomatic group, showing a high sensitivity to COVID-19." (PMID 36646780, 2023). "In COVID-19, patients with confirmed bacterial infections, blood level of neutrophils, CRP, ferritin, IL-1β, IL-2R, IL-6, and TNF-α were higher than the upper limits of the normal values with significant differences, while lymphocyte was significantly lower." (PMID 37771749, 2023). "For example, in the context of COVID-19, CRP POC testing can help to evaluate disease severity or, together with clinical evaluation, suggest the need for hospitalization." (PMID 36673130, 2023). "The findings revealed that the features of C-reactive protein, the ratio of lymphocytes, lactic acid, and serum calcium have a substantial impact on COVID-19 prognostic predictions." (PMID 36116079, 2023). "Severe COVID-19 patients usually present with a hyperinflammatory status, and several studies have proposed CRP as a marker of cytokine storm in these patients." (PMID 37108262, 2023). "According to the work of Fang Liu and colleagues, COVID-19 patients with blood CRP values greater than 41.8 mg/L are the most likely to develop severe disease." (PMID 37662725, 2023). "In a clinical study including 15 COVID-19-positive patients, tocilizumab treatment was found to significantly lower C-reactive Protein (CRP) levels." (PMID 36906872, 2023). "The usage of tocilizumab was stratified by severity of COVID-19; only those patients with signs of advanced systemic inflammation (hypoxia and C-reactive protein ≥75 mg/L) were randomized and treated with tocilizumab in addition to glucocorticoids." (PMID 37507425, 2023).
COVID-19 (continued). "These markers, such as D-dimer, fibrinogen, bilirubin, ferritin or C-reactive protein, were indeed inconstantly measured among COVID-19 positive patients and rarely measured among COVID-19 negative patients." (PMID 36670340, 2023). "Increased WBC and neutrophil counts, lymphocytopenia, increased neutrophil-to-lymphocyte ratio, thrombocytopenia, elevated CRP, ferritin, D-dimer, and IL-6 levels have been associated with MIS and unfavourable clinical outcomes in COVID-19." (PMID 36830885, 2023). "DPP3, IL-6, CRP, and leucocytes were significantly elevated in COVID-19 patients with infiltrate above the median compared to patients with infiltrate below the median (each p < 0.05) and outpatients without imaging (each p < 0.05)." (PMID 37733154, 2023). "Establishing associations between leukocyte indices and biomarkers, such as procalcitonin and C-reactive protein, enables the utilization of routine complete blood counts as a primary screening tool for predicting the severity of COVID-19 in pregnant women." (PMID 37520486, 2023). "On the other hand, CRP levels that are positively correlated with the severity of different infections have been recently described as a good predictor of COVID-19 severity." (PMID 37789255, 2023). "There was a slight positive correlation between IL-6 levels in COVID-19 patients and CRP, fibrinogen, and procalcitonin levels (RS = 0.25, P value .001), (RS = 0.31, P value .001), and (RS = 0.24, P value .001)." (PMID 37960722, 2023). "In regard to inflammatory proteins and their role as biomarkers of COVID-19, protein levels of C-reactive protein (CRP) has been shown to be elevated in approximately 60% of COVID-19 patients with a cut-off point greater than 10 mg/L." (PMID 37168848, 2023). "A comprehensive meta-analysis had shown that the severe or fatal COVID-19 cases were characterized by elevated levels of CRP, ferritin and interleukins while the lymphocyte, eosinophil and platelet counts were decreased." (PMID 37570378, 2023). "Although CRP is generally described as a biomarker for bacterial infection, higher levels of this acute phase protein were observed in COVID-19 patients compared to TB." (PMID 36590898, 2023). "It is known that COVID-19 raises inflammatory markers like d-dimer, fibrinogen, IL-6, and CRP, especially in severe cases, which are considered good indicators for severity and recovery of COVID-19." (PMID 36508011, 2023). "Changes in the concentration of CRP observed in COVID-19 also reflect not only inflammatory processes, but also indicate the presence and course of bacterial coinfection." (PMID 36975366, 2023). "We found that PAR was superior to procalcitonin, WBC, NLR, and CRP in the early recognition of COVID-19 patients requiring ICU care." (PMID 36950410, 2023). "Our data confirm a reduction in the respiratory index PO2/FiO2 and a concomitant increase in IL-6 and CRP levels, a peculiar consequence of the cytokine storm, which are significative indicators for severe COVID-19." (PMID 37631910, 2023). "The aim of our study was to evaluate the prognostic role of MDW, CRP, procalcitonin, and lactate in critically ill COVID-19 patients." (PMID 36769843, 2023). "Serum levels of IL-6, ferritin, ESR, CRP, D-dimer and fibrinogen are significantly higher, as COVID-19 is an inflammatory and prothrombotic state." (PMID 36984473, 2023). "COVID-19 manifests itself with characteristic changes in biochemical indicators, such as high levels of D-dimer, C-reactive protein (CRP), etc., which can be considered predictors of severe disability, multiple organ failure, and fatal outcomes." (PMID 37834324, 2023). "This study revealed that PAR was superior to procalcitonin, WBC, NLR and CRP in determining COVID-19 severity." (PMID 36950410, 2023). "We aimed to determine the ability of inflammatory biomarkers (Il-6, PCT, CRP, and leukocytes) to predict mortality in COVID-19 patients in the ICU." (PMID 37311846, 2023).